INS (insulin)
Diseases named in the same sentence as INS in open-access papers (continued):
Sharing a sentence is not in itself a finding about the gene and the disease.
diabetes (continued). "Type IB sPLA2 is contained in insulin secretory granules of pancreatic islet ß-cells, it is co-secreted with insulin from glucose-stimulated islets and it is expressed in human islets of transplanted pancreas after the recurrence of type 1 diabetes mellitus with insulitis." (PMID 27631977, 2016). "Although maintaining long-term glycemic control with exogenous insulin imposes an enormous physical, psychological, and financial burden on patients, it remains the only option in the face of the serious, life-threatening potential complications of diabetes." (PMID 26756576, 2016). "In this paper, we review the roles of pyruvate, NADH, and complex I in insulin secretion and hypothesize that complex I plays a crucial role in the pathogenesis of β cell dysfunction in the diabetic pancreas." (PMID 26568959, 2015). "At 18 weeks of age, all MT-tg male mice developed significant diabetes; fasting blood glucose levels (zero time) in MT-tg male mice were significantly higher than those observed in WT, and fasting plasma insulin levels (zero time) in MT-tg male mice were much lower." (PMID 26335571, 2015). "Thus, diabetes-induced impairment of insulin functions inhibits glucose uptake into the skeletal muscle, resulting in the disturbances to muscle contractions." (PMID 26075247, 2015). "All of the indicators of disease severity may also progress in intensity with respect to the length of diabetes duration and thus to the duration of insulin exposure." (PMID 26537234, 2015). "Approximately 26 % of adults diagnosed with diabetes receive insulin therapy." (PMID 26120575, 2015). "DIO animals exhibit an altered insulin/glucagon ratio and are resistant to the hypothalamic actions of glucagon on glucose production, suggesting that this resistance contributes to hyperglycemia in diabetes and obesity." (PMID 26909312, 2015). "Fifty seven percent, n=79 participants were taking insulin for managing diabetes." (PMID 26925888, 2015). "Since there is a considerable debate in the literature about whether HFCS in sodas or processed foods contributes to diabetes, we examined glucose tolerance and insulin sensitivity by GTT and ITT." (PMID 26200659, 2015). "There was also some evidence of higher cardiosympathetic stress responses in association with higher maternal insulin concentrations, even in the absence of parental diabetes." (PMID 25478935, 2015). "The discrepancy between previous human studies and our present rat study could be due to the differences in the characteristic features of diabetes: the former is characterized by obesity and insulin resistance, the latter by impaired insulin secretion." (PMID 26366137, 2015). "At laterstages, this overstimulation of insulin secretion might ultimately result in an alterationin glucose metabolism and diabetes development." (PMID 26157580, 2015). "Diabetes education should be considered early, to include glucose monitoring and even insulin administration training, as intermittent use of insulin is common enough that early training may prevent a delay in discharge." (PMID 25721247, 2015). "In the 1,140 patients who were recognized by a physician to have experienced hypoglycemia in the last 1 month and were using diabetes medication as a monotherapy, the highest incidence of hypoglycemia was observed in the patients undergoing insulin monotherapy (32.7%)." (PMID 26566411, 2015). "The extracts can also be tested for their effect on protein–tyrosine phosphatase 1B (PTP1B), a cytosolic enzyme, that not only increase cellular response to insulin, but also elevates leptin signalling and are therefore, a promising strategy for the treatment of diabetes mellitus and obesity." (PMID 25652009, 2015). "Other studies have shown independent predictors for antenatal insulin requirement to be a positive family history of diabetes, multiple abnormal values on the OGTT, the BMI, the time of diagnosis, the fasting glucose on the OGTT and HbA1c at the diagnosis of GDM." (PMID 26497130, 2015).
diabetes (continued). "Those who are already diagnosed with diabetes appear to have evidence of more visceral fat, with more marked adverse metabolic profiles (raised triglycerides), higher frequency of abnormal insulin metabolism and higher fasting blood glucose than those who are undiagnosed." (PMID 26186342, 2015). "Sphingosine kinase knockout mice fed on a high-fat diet presented diabetes, simultaneous significant reduction of pancreatic β cell mass and plasma insulin level, whereas wild type mice developed glucose intolerance, significantly increased mass of pancreatic β cells and hyperinsulinemia." (PMID 26076974, 2015). "Insulin resistance is an early feature of diabetes progression and our results call attention for further studies addressing the axis glucagon-cAMP-GSH as new therapeutic target for the treatment of insulin resistant states, a hallmark of type 2 diabetes and obesity." (PMID 25961284, 2015). "Furthermore, suppression of insulin signaling pathway with diabetes was confirmed by western blotting analysis of some components in AKT-PI3K pathway." (PMID 26715102, 2015). "Therefore, a quantitative analysis of key proteases during insulin maturation will help clarify the functional status of pancreatic islet β cells, enabling pathogenesis studies of diabetes." (PMID 26942221, 2015). "The most common reasons given in this study for presenting in DKA in patients with pre-existing diabetes were problems with interruption of insulin delivery (e.g. kink in tubing, bent cannula, and cannula insertion site problems such as lipohypertrophy), infection and non-adherence." (PMID 25889476, 2015). "Among the clinical drugs used in the treatment of type 2 diabetes mellitus, thiazolidinediones, such as rosiglitazone (Ros) and pioglitazone, can be used as PPARγ agonists to significantly reduce hypoglycemia and improve the sensitivity to the insulin pathway." (PMID 25574213, 2015). "According to the number of insulin injections a day and glycaemic self-control measurements, various subcategories of the diabetes convention exist, e.g. convention 3A concerns patients with two or more insulin injections a day and more than 30 glycaemic measurements a month." (PMID 26171143, 2015). "In addition, modulation of insulin secretion is very important to improve chronic diseases such as diabetes, obesity and cardiovascular diseases." (PMID 26024293, 2015). "Therefore, this study aims to examine this issue and to assess the measurement properties of the 5L in comparison with the 3L among diabetes mellitus patients treated with insulin." (PMID 25890017, 2015). "Therefore, modulation of gastric emptying and enhancement of insulin effects to minimize dietary postprandial glucose elevation has a potential to optimize glycemic control in diabetes." (PMID 26441829, 2015). "These disparities in need for add-on insulin with metformin may be explained by differences in populations studied because diabetes and its control vary widely in different populations related to their genetic and phenotypic makeup." (PMID 25874236, 2015). "We conducted sensitivity analyses to examine whether trends in ED visit rates for both conditions differed when the denominator for rates was restricted to the respondents with diabetes who were being treated with insulin or oral medication." (PMID 26252486, 2015). "Streptozotocin selectively damages pancreatic insulin-secreting β-cells leading to diabetes." (PMID 26682215, 2015). "A randomized, double-blind study in 12 psoriatic patients at high risk of developing type 2 diabetes mellitus failed to see a significant effect of a 2-week treatment with etanercept on insulin secretion and sensitivity." (PMID 25654080, 2015). "The role of insulin therapy over HRQoL of patients with diabetes is controversial." (PMID 26110026, 2015).
diabetes (continued). "Patients with type 2 diabetes in pregnancy were selected with strict inclusion criteria; that is, they were not on insulin treatment and did not have complications associated with diabetes." (PMID 25874236, 2015). "We calculated sensitivity and specificity of diabetes diagnosis based on HbA1c compared with diagnosis based on glucose among previously undiagnosed individuals (ie, excluding those with history of diabetes or using insulin or oral hypoglycaemic drugs)." (PMID 26109024, 2015). "Obesity, diabetes, insulin, liver disease, increased triglycerides, endothelial stimulation (exercise, V2 receptor analogs, and surgery), fibrinogen, intravascular haemolysis, chronic inflammation, malignancy, hyperthyroidism, and renal disease also cause increase in factor VIII levels." (PMID 26421318, 2015). "Diabetes is a chronic disease characterized by insufficient production of insulin or by an inability to effectively use the produced insulin, which leads to hyperglycemia and in time to the occurrence of serious damage to several of the body's systems and especially the nerves." (PMID 26435566, 2015). "South Asians are characterized by a unique metabolic profile with higher insulin levels, a greater degree of insulin resistance, greater abdominal adiposity i. e., higher waist circumference despite lower body mass index and a higher prevalence of diabetes." (PMID 26020947, 2015). "Thus, we conclude that the cryopreserved human islet grafts retained at least some function in vivo, but the reversal of diabetes was limited by the reduced insulin content of these islets." (PMID 25930156, 2015). "The present review focuses mainly on drivers who require insulin treatment for their diabetes." (PMID 28702227, 2015). "Therefore, the evidence suggests that GB and G0 should be treated as separate entities for individuals with established diabetes as the levels are determined by relative insufficiencies in SI, endogenous insulin secretion (UN) and rates of gluconeogenesis." (PMID 25881031, 2015). "For patients withperioperative ischemic stroke the mean age was 64 years, 9 (40.9%) patients were femaleand 13 (59.1%) were male, 10 (45.6%) had diabetes on insulin, 3 (13.63%) had CS greaterthan 70%; 9 (40.9%) had peripheral artery disease and 18 (81.8%) patients underwentsurgery with CPB." (PMID 26313728, 2015). "PF and IF have few adverse effects, but could be dangerous for subjects of very low BMI, those who are frail and old, and patients with diabetes receiving insulin or insulin-like drugs." (PMID 25902704, 2015). "When performing a multivariate logistic regression analysis, peripheral neuropathy demonstrated the highest significant OR (95% CI) at 8.03 (5.47–11.78) followed by insulin usage, age ≥45 years, diabetes duration ≥10 years, retinopathy, and poor glycemic control." (PMID 25946144, 2015). "It is known that, in diabetes, insulin's regulation over lipolysis is lost." (PMID 25866533, 2015). "One-third of the respondents to our survey refer patients who need insulin to diabetes specialists." (PMID 25877332, 2015). "To test the performance of Visinets graphical approach we have; a) built the “de novo” model of EGFR and Erk1/2 signaling with manual parameter adjustment and; b) translated existing model of insulin signaling in diabetes from published ODE model into CMAP formalism." (PMID 26020230, 2015). "Stroke occurred in 4.2% of patients and the risk factors statistically significantwere: carotid stenosis of 70% or more (P=0.03; OR 5.07; IC 95%:1.35 to 19.02), diabetes on insulin (P=0.04; OR 2.61; IC 95%:1.10 to 6.21) and peripheral arteriopathy (P=0.03; OR 2.61; 95%CI: 1.08 to 6.28)." (PMID 26313728, 2015). "While mortality was numerically higher in diabetes patients and highest in insulin treated diabetes, the sample size and event rate limited our ability to show any clinically significant differences that might exist." (PMID 26074965, 2015).
diabetes (continued). "miR-22 can regulate the PTEN/AKT pathway and target HDAC6; miR-206 and miR-1a can suppress hepatic lipogenesis; miR-29b and miR-9 are involved in insulin sensitivity and diabetes; miR-31 and miR-32 participate in differentiation of stem cells into adipocyte and lipid metabolism in oligodendrocytes." (PMID 25675096, 2015). "Therefore, determining the perception of disease, and concerns about diet, insulin use, exercise, and future are important for the patients’ diabetes management." (PMID 26005688, 2015). "Personen mit Typ 1 oder insulin-behandeltem Typ 2 Diabetes ( > 15 Lj)." (PMID 25421366, 2015). "These reductions in insulin doses may serve to motivate patients regarding both medication and dietary compliance, as they gain the confidence to know that their diabetes can be effectively managed." (PMID 26222846, 2015). "In its early “pre-diabetes” stage, elevated glucose levels co-occur with elevated insulin due to defective insulin responses in insulin target tissues, notably skeletal muscle, liver and fat, and by defects in insulin secretion from pancreatic β-cells." (PMID 25830378, 2015). "Diabetes mellitus type 2 is also known as non-insulin-dependent diabetes mellitus which is caused by insulin dysfunction, especially after food intake." (PMID 25887244, 2015). "Elevated levels of PP secretion observed in diabetics is hypothesized to be a compensatory mechanism to increase insulin release and improve glycemic control; this may also enhance brain insulin signaling and glucose metabolism, and thereby reduce MCI risk." (PMID 26441635, 2015). "Further prospective studies are required to evaluate whether weight control in adolescents actually improves insulin sensitivity and prevents the onset of diabetes." (PMID 25970186, 2015). "In spite of the fact that insulin is the most important therapeutic agent known to medicine, researchers have been making efforts to find insulin-like substances from plant sources for the treatment of diabetes." (PMID 26347423, 2015). "We could nevertheless speculate that, by reducing insulin requirements and plasma and capillary glucose levels, the use of specific formulas for diabetes would be useful for this purpose." (PMID 26549276, 2015). "Metformin, which is widely used in the treatment of diabetes, ameliorates insulin sensitivity." (PMID 25879666, 2015). "During the 4 week intervention period following the onset of diabetes, the insulin-treated mice maintained on a HFD continued to gain weight, more body fat, and even higher fasting insulin, C-Peptide, and leptin levels (2C & D) whereas sham-treated diabetic mice showed a tendency to lose weight." (PMID 25633992, 2015). "Everyday challenges for patients with childhood-onset type 1 diabetes mellitus (T1D) include the regular monitoring of blood glucose; the balancing of insulin administration, food intake and physical activity; and the fear of acute and late diabetes-related complications." (PMID 26121155, 2015). "With insulin pump therapy provided during hospitalization it is possible to standardize the sugar control profile in patients with type 2 diabetes mellitus in a short period of time, thereby allowing for the further evaluation of the clinical response to GLP-1 analogues." (PMID 25785276, 2015). "One study reported that the diabetes risk allele of ADAMTS9 was associated with reduced insulin sensitivity but not with insulin secretion." (PMID 26218657, 2015). "Downregulation of RANKL in nutritional and genetic animal models of insulin resistance and type 2 diabetes mellitus revealed a marked improvement in hepatic insulin sensitivity and amelioration or even normalization of glucose concentrations and tolerance and insulin signaling." (PMID 25873952, 2015).
diabetes (continued). "However, other long-term injectable treatments, such as insulin therapy for diabetes, are already in use for millions of patients, allowing us to predict that it will not be difficult to adjust the siRNA treatments also for the long-term use." (PMID 26325626, 2015). "As previous studies that compared subjects with and without this diabetic late complication, those with retinopathy had longer diabetes duration, had higher glycated hemoglobin concentrations, and were more frequently on antihypertensive and insulin treatments." (PMID 26078978, 2015). "This study clearly demonstrated that the 4-week short-term comprehensive intervention with liraglutide and lifestyle management could provide significant improvement of insulin sensitivity in uncontrolled diabetes patients." (PMID 25922845, 2015). "The results from our single, health-service funded centre in Scotland confirms that islet transplantation significantly reduces severe hypoglycaemia and exogenous insulin requirements, and improves diabetes control (as reflected by the HbA1c and CGMS profiles, with evidence of C-peptide secretion)." (PMID 25810037, 2015). "Decreased pancreatic insulin reserve and action could precipitate hypo-insulinaemic diabetes, and late stage TIIDM." (PMID 25867198, 2015). "By logistic regression, apart from rs12979860 CC, older age, high insulin, high blood glucose, high HOMA-IR, low platelet counts, AST, GGT, ALT, the presence of hypertension, the presence of diabetes and portal inflammation were associated with significant fibrosis." (PMID 25740255, 2015). "Recent research has provided evidence that insulin resistance and impaired insulin signalling may be a contributory factor to the progression of diabetes, dementia, and other neurological disorders." (PMID 26693205, 2015). "Diabetic ketoacidosis (DKA) is a serious complication of diabetes, resulting from a severe lack of insulin and is the most common cause of morbidity and mortality in youth with type 1 diabetes mellitus (T1DM)." (PMID 26323283, 2015). "The prognosis of breast cancer may also be affected by diabetes status and fasting serum insulin level." (PMID 26171401, 2015). "The more prominent relation between GDR and myocardial FDG uptake than between myocardial FDG uptake and FFA in patients with diabetes suggested that insulin resistance regulates the myocardial cellular glucose FFA cycle, the so-called Randle cycle, and/or levels of plasma FFA." (PMID 26538247, 2015). "Besides a higher BMI-SDS and a lower frequency of insulin pump therapy in offspring with migrant background, differences in specific areas of diabetes therapy and outcome were observed depending on the region of origin." (PMID 26295472, 2015). "Diabetes mellitus is a metabolic disorder of multiple etiologies, characterized by chronic hyperglycemia with disturbances in carbohydrate, fat, and protein metabolism, resulting from defects in insulin secretion, insulin action, or both." (PMID 26649063, 2015). "High blood insulin and glucose are damaging to blood vessel function thus T2DM is considered a risk factor for cardiovascular disease, with 60–80% of people with diabetes having hypertension and around 75% of deaths in this population due to cardiovascular disease." (PMID 26196519, 2015). "Moreover, insulin therapy being monopolized in diabetes centres, GPs risked to lose the necessary competences to initiate and follow-up insulin therapy." (PMID 26171143, 2015). "The expression of ADPNR-1 and ADPNR-2 are decreased both in obese mice and humans, and decreased ADPNRs in obesity can reduce adiponectin sensitivity, which ultimately leads to diminished insulin sensitivity, whereas up-regulating ADPNRs can ameliorate the symptoms of diabetes." (PMID 25849026, 2015). "We speculate that alpha-lipoic acid might have an antioxidant effect in pediatric diabetes patients by reducing insulin." (PMID 26171398, 2015).